PTK7 (protein tyrosine kinase 7 (inactive))
Diseases named in the same sentence as PTK7 in open-access papers (continued):
Sharing a sentence is not in itself a finding about the gene and the disease.
colon carcinoma (25 papers, 2010 to 2025). "Although this study contradicts another study regarding the effect of PTK7 on the prognosis of colon cancer, the association of PTK7 with clinicopathological characteristics seems to provide evidence for this." (PMID 39474113, 2024). "A previous study found that PTK7 was not only associated with better OS in colon cancer but also with good tumor differentiation, less lymph node metastasis and distant metastasis, and early TNM stage." (PMID 39474113, 2024). "An example of this scenario is the rs6905948 variant (IDI 0.091, p-value: 0.059), in the PTK7 (Protein Tyrosine Kinase 7) gene, known to be implicated in colon carcinoma as well as in some types of anxiety-related disorders." (PMID 30824863, 2019). "PTK7 was initially identified as a gene upregulated in colon carcinoma cells and was, therefore, named colon carcinoma kinase 4 (CCK-4)." (PMID 39474113, 2024). "Protein tyrosine kinase 7 (PTK7) is a member of the receptor protein tyrosine kinase family, initially identified as an inactive kinase in colon cancer cells and melanoma cells." (PMID 39135992, 2024). "Early work by our team elucidated the prominent role of PTK7 in drug resistance in leukemia and later on in colon cancer." (PMID 38773263, 2024). "PTK7 knockdown reduces the proliferation and anti-apoptotic activity of colon cancer cells and inhibits the proliferation, migration, and invasion of liposarcoma cells." (PMID 37569547, 2023). "PTK7 is involved in cell proliferation, migration, and/or resistance to apoptosis in leukemia cells, colon cancer cells, liposarcoma cells, cervical cancer cells, and thyroid cancer cells." (PMID 37569547, 2023). "Starting with the identification of PTK7 as a gene upregulated in colon carcinoma cells, PTK7 expression has been shown to be deregulated in a number of cancer cell types." (PMID 34502237, 2021). "Originally, PTK7 was identified as a gene upregulated in colon carcinoma cells and accordingly named colon-carcinoma kinase 4 (CCK4)." (PMID 34502237, 2021). "Although the mechanism is still elusive, previous research showed that the proliferation and migration of colon cancer cells can be mediated by PTK7 cleavages." (PMID 33947097, 2021). "Protein tyrosine kinase-7 (PTK-7) is a protein that was first discovered in colon carcinoma cell lines." (PMID 31820857, 2020). "PTK7 was identified as a gene upregulated in colon carcinoma cells and appears to be misregulated in a variety of cancers." (PMID 28424771, 2017). "PTK7 (protein tyrosine kinase 7) is an orphan tyrosine kinase receptor, first identified in colon carcinoma cells and also named colon carcinoma kinase-4 (CCK-4)." (PMID 24465953, 2014). "PTK7 expression is upregulated in many common human cancers, including colon cancer, lung cancer, gastric cancer, and acute myeloid leukemia." (PMID 24587299, 2014). "It has been demonstrated that PTK7 overexpression is observed in several cancers including colon cancer, gastric cancer, lung cancer, acute myeloid leukemia, esophageal squamous cell cancer, and liposarcoma." (PMID 24987951, 2014). "It was also demonstrated by others that PTK7 silencing induced apoptosis in colon cancer HCT-116 cells, reinforcing that PTK7 regulates cell survival." (PMID 24618420, 2014). "The receptor protein tyrosine kinase 7 (PTK7), a pseudokinase, also known as colon carcinoma kinase, was originally identified as a protein overexpressed in colon cancer cell lines." (PMID 24987951, 2014). "A previous study proved that the silencing of PTK7 can lead to the inhibition of cell proliferation and apoptosis in colon cancer cells." (PMID 24587299, 2014). "Protein tyrosine kinase 7 (PTK7) is a transmembrane receptor initially identified in colon carcinoma as colon carcinoma kinase-4, CCK4." (PMID 23209741, 2012). "In fact, PTK7 has been identified as a gene expressed in primary colon carcinoma, and overexpression of PTK7 is often found in colon carcinoma cells." (PMID 21103379, 2010).
colon carcinoma (continued). "PTK7 is upregulated in many common human cancers, including colon cancer, lung cancer, gastric cancer and acute myeloid leukemia." (PMID 21103379, 2010). "The expression of PTK7 is up-regulated in many common human cancers, including colon cancer, lung cancer, gastric cancer and acute myeloid leukemia." (PMID 21103379, 2010). "APC mutant colon cancer organoids are characterized by upregulated PTK7 expression, suggesting that PTK7 targeting may be beneficial for APC mutant colorectal cancer patients." (PMID 39474113, 2024). "In colon cancer, PTK7 expression implies poor metastasis-free survival (MFS)." (PMID 39474113, 2024). "Notably, PTK7 has been identified as a prognostic marker for colon cancer, suggesting its utility in forecasting the disease onset." (PMID 38740744, 2024). "A recent study demonstrated that protein tyrosine kinase 7 (PTK7), a critical membrane receptor that was first discovered in colon carcinoma cell lines, improved the sensitivity of detecting CTCs in gastric cell line samples combined with epithelial cell adhesion molecule (EpCAM)." (PMID 36302755, 2022). "The human Otk orthologue was originally named Colon Carcinoma Kinase 4 (CCK4), a gene highly upregulated in colon cancers, but was renamed Protein Tyrosine Kinase 7 (Ptk7) because its protein structure places it among a single-pass transmembrane receptor family with a deficient kinase domain." (PMID 27438854, 2016). "• Niche indications for ADCs included targets for CD71, PSMA, PTK7 or CD74, in breast, lung, stomach or colon cancer." (PMID 37740463, 2023). "We previously reported that a cytosolic domain (CTF2) of PTK7 generated by sequential cleavage by ADAM17 and γ-secretase translocates into nucleus and enhances oncogenic phenotype of colon cancer cells." (PMID 27689325, 2016). "The receptor protein tyrosine kinase PTK7, also known as CCK4, was discovered as a gene overexpressed in colon cancer cell lines." (PMID 24409301, 2014). "Expression of PTK7 in HCT 116, human colon carcinoma cells, was investigated by flow cytometry (untreated) and Western blot (0 h)." (PMID 21103379, 2010). "PTK7 was initially identified in human colon carcinoma tissue and its derived cell lines, but it is not expressed in normal adult colon tissue." (PMID 28545451, 2017). "In colon cancer and ovarian cancer, PTK7 sensitizes canonical Wnt and non-canonical Wnt/PCP pathways, respectively." (PMID 27689325, 2016). "The cell surface receptor PTK7, also known as colon carcinoma kinase-4 (CCK-4), is an evolutionary conserved member of the receptor tyrosine kinase superfamily, which was first identified in human normal melanocytes and in human colon carcinoma." (PMID 25962058, 2015). "Surprisingly, whereas PTK7 was first described in human colon cancer cell lines, no data are currently regarding its protein expression in CRC tissues from clinically annotated patients." (PMID 25962058, 2015). "In addition, PTK7 and SLC44A4 showed high expression in breast and colon tumours." (PMID 37740463, 2023). "In addition, PTK7-CTD enhances the proliferation and migration of colon cancer cells." (PMID 33947097, 2021). "In addition, both full-length and proteolytic PTK7 fragments were detected in human colon cancer tissues and it was hypothesized that the ratio of proteolytic fragments to full-length forms, rather than PTK7 total expression, could be biomarker in cancer." (PMID 25962058, 2015).
acute lymphoblastic leukemia (20 papers, 2013 to 2026). Leukemia with an acute onset, characterized by the presence of lymphoblasts in the bone marrow and the peripheral blood. "For acute lymphoblastic leukemia, an oncological disease prevalent in children, a redox-labeled electrochemical aptasensor that specifically detects the cancer biomarker protein tyrosine kinase 7 (PTK7) was developed." (PMID 37175137, 2023). "A proof-of-concept study has been carried out on CCRF-CEM cells (human acute lymphoblastic leukaemia T cells which overexpress protein tyrosine kinase 7 (PTK7)) using AAPs based on a conformation-switchable sgc8c aptamer, targeting PTK7, labelled with a fluorophore/quencher pair." (PMID 29261171, 2017). "In an acute lymphoblastic leukemia (ALL) model, sgc8 aptamer-functionalized liposomes were developed to target PTK7, which is abundantly expressed on T-cell precursors." (PMID 41560835, 2026). "ROR2 expression was also shown to activate AKT signaling in multiple myeloma, whereas PTK7 expression elicits anti-apoptotic effects in T cell acute lymphoblastic leukemia (T-ALL)." (PMID 35504983, 2022). "For example, as a potential cancer marker for T-cell acute lymphoblastic leukemia (T-ALL), the protein tyrosine kinase 7 (PTK7) has been identified." (PMID 34073054, 2021). "We studied the interaction of the specific DNA aptamer sgc8c immobilized at the AFM tip with its corresponding receptor, the protein tyrosine kinase-7 (PTK7) embedded in the membrane of acute lymphoblastic leukemia (ALL) cells (Jurkat T-cells)." (PMID 28229174, 2017). "Such strategy was used by our group to identify a biomarker for T-cell acute lymphoblastic leukemia (T-ALL), the transmembrane protein tyrosine kinase 7 (PTK7)." (PMID 23401749, 2013). "Through conjugation to the membrane PTK7-specific aptamer Sgc8c, the device was used to detect CCRF-CEM cells (human acute lymphoblastic leukemia cells), which express PTK7." (PMID 31847897, 2019). "Furthermore, in the context of acute lymphoblastic leukemia (ALL), miR-205 targets the PTK7 gene." (PMID 41001034, 2025). "Aptamers against the extracellular region of PTK7 have been identified and one of them, an ssDNA sequence composed of 42 nucleotides named Sgc8c, was demonstrated to specifically eradicate Acute Lymphoblastic Leukemia (ALL) cells when coupled to doxorubicin, a drug used to treat this disease." (PMID 38773263, 2024). "Sgc8 aptamer was selected to bind to human protein tyrosine kinase-7 (PTK7), which is a specific biomarker of acute lymphoblastic leukemia (ALL) T cells." (PMID 32585627, 2020). "Sgc8c is a DNA aptamer that specifically binds to protein tyrosine kinase 7 (PTK7) on the surface of CCRF-CEM (T-cell acute lymphoblastic leukemia, T-cell ALL) cells with high binding affinity." (PMID 26473828, 2015).
leukemia (19 papers, 2014 to 2026). A malignant (clonal) hematologic disorder, involving hematopoietic stem cells and characterized by the presence of primitive or atypical myeloid or lymphoid cells in the bone marrow and the blood. "The prognostic value of PTK7 is not only in solid tumors, but also in acute myeloid leukemia, where its expression is an independent risk factor for leukemia free survival (LFS) and OS in patients." (PMID 39474113, 2024). "Protein tyrosine kinase 7 (PTK7) identified by aptamer Sgc8 in leukemia cell possibly makes aptamer Sgc8 become a diagnostic biomarker in the future." (PMID 33796540, 2021). "In vitro experiments exploring the roles of PTK7 showed that PTK7 promotes leukemia cell migration, cell survival, and resistance to anthracycline-induced apoptosis." (PMID 39474113, 2024). "The sgc8 aptamer was then selected to identify the human protein tyrosine kinase-7 (PTK7) as a binding target protein present on the leukemia cell surface." (PMID 35056696, 2022). "Most straightforward is the detection of cancer cells using antibodies or nucleic acid aptamers specific to certain cancer markers, such as PTK7 proteins in the membranes of leukemia cells." (PMID 34073054, 2021). "PTK7 has been reported to be upregulated in multiple cancers, including those of colon, lung, gastro, and leukemia." (PMID 28545451, 2017). "We recently described a similar poor-prognosis impact for PTK7 expression in AML patients, in whom it was associated with a higher relapse rate and reduced leukemia-free survival and OS." (PMID 25962058, 2015). "Ectopic overexpression of PTK7 in leukemia cells promotes cell migration and survival, whereas knockdown of PTK7 shows the opposite effects." (PMID 24987951, 2014). "The expression of PTK7 in leukemia cells enhances cell migration and survival." (PMID 37569547, 2023). "High expression of JUP, NT5C3B, MYC, GATA3, PTK7, CNP, and ICOSLG clearly differentiated the leukemia from the non-leukemia group." (PMID 41596324, 2026). "Statistically significant differences between the leukemia and MRD-negative groups were achieved by JUP, NT5C3B, MYC, GATA3, PTK7, CNP, SNAI1, and ICOSLG." (PMID 41596324, 2026). "In our recent work we showed that TSM method is rather useful for detection leukemia Jurkat and MOLT-4 cell lines containing protein tyrosine kinase 7 (PTK7) receptors based on DNA aptamers specific to PTK7." (PMID 31137893, 2019). "PTK7 is expressed in some human acute myeloid leukemia (AML) patients, who are more resistant to anthracycline-based frontline therapy with a significantly reduced leukemia-free survival." (PMID 24465953, 2014). "Importantly, JUP, NT5C3B, MYC, and GATA3, PTK7, CNP, and ICOSLG differentiated both non-pathological conditions (non-leukemia and MRD-negative) from leukemia samples." (PMID 41596324, 2026).
ovarian carcinoma (19 papers, 2016 to 2026). A malignant neoplasm originating from the surface ovarian epithelium. "Preclinical studies have demonstrated that cofetuzumab pelidotin effectively reduces tumor growth in PTK7-expressing tumors, including those derived from ovarian cancer." (PMID 41347223, 2025). "Experimental evidence underscores FOXP4’s role as a transcriptional activator of PTK7, thereby facilitating ovarian cancer progression." (PMID 38740744, 2024). "In ovarian cancer, PTK7 CAR-T cells based on TREM1/DAP12 signaling exhibited potent cytotoxicity against PTK7+ cancer cells." (PMID 39474113, 2024). "With ongoing research, PTK7 holds promise as a potential therapeutic target not only for ovarian cancer but potentially for a broader range of tumor types." (PMID 38740744, 2024). "Regulatory mechanisms involving the transcription factor FOXP4 have been shown to modulate PTK7, contributing to the malignant progression of ovarian cancer, though the specifics of downstream signaling regulation remain uncertain." (PMID 38740744, 2024). "Taken together, our study provides unique insight into the function of PTK7, which helps to define its role in mediating aberrant Wnt signaling in ovarian cancer." (PMID 35977930, 2022). "In other cancer types PTK7 was shown to be downregulated, including lung squamous cell carcinoma, ovarian carcinoma and metastatic melanoma." (PMID 28424771, 2017). "Similarly, i.p. treatment of [212Pb]Pb-TCMC-chOI-1 targeting protein tyrosine kinase 7 (PTK7) was evaluated for the treatment of ovarian cancer, showing tumor retention and uptake into the systemic blood circulation after i.p. injection." (PMID 41510167, 2026). "This series of changes revealed that β-catenin/FOXP4/PTK7 signaling pathway may affect the invasion ability of ovarian cancer cells by regulating EMT process." (PMID 38740744, 2024). "Thus, several critical inquiries arise: Is there a direct linkage between PTK7 and the onset of ovarian cancer?" (PMID 38740744, 2024). "A study found that the combination of other targeted or chemotherapeutic agents to anti-PTK7 mAb may increase the pharmacological efficacy compared to single-agent treatment in ovarian cancer." (PMID 39474113, 2024). "In epithelial ovarian cancer, PTK7 is highly expressed in type I tumors." (PMID 39474113, 2024). "PTK7 has been identified as a potential therapeutic target, and a PTK7 antibody drug conjugate (PF-06647020; cofetuzumab pelidotin) has been investigated in phase I clinical trials for triple-negative breast cancer, ovarian cancer, and non-small cell lung cancer." (PMID 39335176, 2024). "Very interestingly, PTK7 has recently been established as a marker for normal colon stem cells and as a marker for tumor initiating cells in triple-negative breast cancer, ovarian cancer and non-small cell lung cancer." (PMID 28424771, 2017). "However, PTK7 is downregulated in lung squamous cell carcinoma and ovarian carcinoma." (PMID 35257502, 2022). "Therefore, the changes in PTK7 expression in ovarian cancer remain unclear." (PMID 39474113, 2024). "Protein tyrosine kinase 7 (PTK7) is a conserved catalytically defective transmembrane receptor that is a potential therapeutic target in triple-negative breast cancer, ovarian cancer, and non-small cell lung cancer." (PMID 39335176, 2024). "This, in conjunction with PTK7’s activation of the β-catenin pathway, establishes a β-catenin/FOXP4/PTK7 positive feedback loop, culminating in the accelerated advancement of ovarian cancer." (PMID 38740744, 2024). "PTK7 is enriched in tumor-initiating cells from patient-derived xenografts of TNBC, ovarian cancer, and non-small-cell lung cancer." (PMID 37569547, 2023). "PF-06647020, a humanized anti-PTK7 ADC, has been developed and is currently being evaluated in clinical trials for the treatment of ovarian cancer, triple-negative breast cancer, and non-small cell lung cancer." (PMID 36139622, 2022).
ovarian carcinoma (continued). "In our study, we identified the genes with a mutation frequency ranking in the top 5 of 100 PTK genes in EOC, namely, MST1R, INSR, RET, PDGFRB, and PTK7, among which we studied the overlooked oncogenic role of RET in ovarian cancer." (PMID 32293499, 2020). "PF-06647020 is an ADC directed against protein tyrosine kinase 7 (PTK7) which is overexpressed in a variety of tumors including lung, CRC, breast, and ovarian cancers." (PMID 29329556, 2018). "Analysis of the GEPIA database revealed that PTK7 mRNA expression was lower in ovarian cancer than in non-cancerous tissues after combining normal samples from the GTEx database with the TCGA cohort." (PMID 39474113, 2024). "A study has found that PTK7 expression is higher in the stem-A subgroup than in non-stem-A subgroup, suggesting that PTK7 is closely related to the stemness of ovarian cancer." (PMID 39474113, 2024). "In the case of epithelial ovarian cancer, a lack of PTK7 expression correlates with advanced disease stages and the presence of metastases." (PMID 38740744, 2024). "Moreover, the involvement of PTK7 in EMT has been reported in hepatocellular carcinoma and ovarian cancer." (PMID 37569547, 2023). "In contrast, Ptk7 is downregulated in some subtypes of ovarian cancers and melanomas, but not other ovarian cancer subtypes." (PMID 27438854, 2016). "In ovarian cancer (OVCA), changes in PTK7 expression are still unknown." (PMID 39474113, 2024). "These ADCs have been directed against specific antigens expressed in several solid tumors including ovarian cancer, among which the most investigated are cancer antigen 125 (CA125 or MUC16), NaPi2b, Trop2, TF, protein tyrosine kinase 7 (PTK7), CD166 and Notch3." (PMID 36046840, 2022).